INS (insulin)
Diseases named in the same sentence as INS in open-access papers (continued):
Sharing a sentence is not in itself a finding about the gene and the disease.
Hypoglycemia (continued). "Incretin-based therapies, GLP-1 receptor (GLP-1R) agonists and DPP-4 inhibitors, enhance the glucose-dependent insulin secretion and optimize the management of glycemic control without hypoglycemia and weight gain." (PMID 24884787, 2014). "Actually, caloric intake lowering (gastroparesis, intravenous glucose, or enteral nutrition lowering) without insulin adjustment may be one of the most frequent risk factors for hypoglycemia, and no study evaluated the effect of gluco-insulinotherapy on hypoglycemia rate." (PMID 25177798, 2014). "However, 39 (25.5%) patients reported having experienced minor hypoglycemia during Ramadan and of which 17 (43.6%) were on combination regimen of OHA and insulin, 14 (35.9%) were on OHA alone, and 8 (20.5%) were on insulin alone." (PMID 25435876, 2014). "The use of [glucose] and the treatment of hyper- and hypoglycemia with insulin without consideration of individual flux can potentially result in medical care that creates the condition that is then subsequently treated." (PMID 25709562, 2014). "Nevertheless, Chan and colleagues have clearly demonstrated that suppression of GABAergic drive in the VMH enhances the secretion of glucagon and adrenaline but not corticosterone in response to insulin-induced hypoglycemia." (PMID 24616659, 2014). "A nationwide cohort study demonstrated that patients who experience hypoglycemia are more likely to be using insulin and sulfonylureas than those who do not experience hypoglycemia." (PMID 25433668, 2014). "Likely one of the main reasons why clinical trials and meta-analyses showed negative results for TGC was the high incidence of hypoglycemia induced by intensive insulin therapy." (PMID 25074071, 2014). "Our current meta-analysis demonstrates that geriatric patients can be treated safely with insulin lispro, with no age-related differences in either the rate or the incidence of overall hypoglycemia." (PMID 23959960, 2014). "Therefore, in the settings of both insulin-and fasting-induced hypoglycemia, GKA23 can still effectively stimulate endogenous insulin secretion." (PMID 24533087, 2014). "A common pitfall in the diagnosis of HI is that insulin concentration is not always elevated, even at the time of hypoglycemia, thus the diagnosis should be based on other indicators of increased insulin action." (PMID 23384201, 2013). "In addition, if hypoglycemia persists for more than two hours, there is an increase in the blood concentration of cortisol and growth hormone and the combination of glucagon, epinephrine, cortisol, and growth hormone could overcome the inhibitory effect of insulin on LGP." (PMID 24062772, 2013). "There were 2 cases of severe hypoglycaemia (approximately 0.1% of patients) in the insulin/exenatide combination group and no cases reported in those using exenatide without insulin." (PMID 23061470, 2013). "Firstly, incretin therapy does not induce hypoglycemia, because it controls blood glucose regulation by both insulin and glucagon secretion depending on the blood glucose level." (PMID 23445717, 2013). "Isolated GHD may present with hypoglycaemia, but both GH excess and long-term adult GHD are insulin-resistant states." (PMID 24616775, 2013). "In a study with diabetic obese db/db mice, 83% reduction of glucagon receptor expression by antisense oligonucleotides did not induce hypoglycemia despite injection of exogenous insulin." (PMID 23744070, 2013). "High risk of hypoglycemia can be predisposed by the use of insulin, whereas oral agents particularly metformin, thiazolidinediones, and DPP-4 inhibitors, are not prone to result in hypoglycemia." (PMID 23876067, 2013). "Glucose-stimulate insulin secretion occurs without hypoglycemia because insulin secretion drops rapidly and is nearly abolished as blood glucose concentrations fall to low levels." (PMID 24260546, 2013).
Hypoglycemia (continued). "A previous study of 122 people taking antidiabetes medication without insulin estimated that, on average, three hypoglycaemia-induced traffic accidents occur per 10 million km driven." (PMID 23121373, 2013). "Despite development of educational programs, insulin analogues and new insulin delivery systems, the frequency of severe hypoglycemia has not decreased over the past decades." (PMID 23577069, 2013). "Surprisingly, the basal VMH ROS level was not altered after recurrent episodes of insulin-hypoglycemia." (PMID 23894333, 2013). "To better understand the mechanisms of IIH we developed an experimental model in which hypoglycemia was obtained by an intraperitoneal injection of a pharmacological dose of regular insulin in nondiabetic Wistar rats." (PMID 24062772, 2013). "Difficulty of maintaining glycaemic control while minimizing hypoglycemia, weight gain as an anabolic effect of insulin, and non-compliance with diet, can also contribute to poorer control with insulin." (PMID 23725198, 2013). "Among patients not using a sulphonylurea, they reported a hypoglycaemia incidence of 33% when lixisenatide QD was added to basal insulin compared with 28% for placebo and basal insulin." (PMID 23061470, 2013). "On the other hand, there are some cases where the episodes of hypoglycemia are a consequence of the presence of high levels of insulin autoantibodies (IAA) to endogenous insulin, despite never having received insulin injections." (PMID 24386337, 2013). "In the absence of IGF2 assays, low serum insulin in combination with low IGF1 levels at the time of hypoglycemia is helpful in making the diagnosis of NICTH." (PMID 24616774, 2013). "Although hProC(A7)Y-CpepGFP transgenic mice did not gain weight during the therapy and did not develop hypoglycemia after therapy withdrawal (not shown), plasma C-peptide level almost doubled 2 days after insulin therapy withdrawal." (PMID 23408938, 2013). "Controlling the blood glucose level of diabetic patients on HD is difficult, because of frequent hypoglycemia, restriction of the use of anti-diabetic agents, and instability of glucose, insulin, and drug metabolites between the day of HD and the non-HD day." (PMID 23445717, 2013). "There were no documented hypoglycaemia episodes reported among subjects who were not on insulin or a sulphonylurea agent." (PMID 23464594, 2013). "The report that glucagon secretion evoked by insulin-induced hypoglycemia is not very different in control mice and in mice lacking insulin receptors in α cells provides additional evidence for a dissociation between insulin and glucagon secretion." (PMID 24315372, 2013). "One week after STZ injection, rats were subjected to moderate hypoglycemia by insulin injection (10U/kg, i.p.)without anesthesia for five consecutive days." (PMID 24278448, 2013). "In a study comparing the GH response of a group of children with spontaneous hypoglycemia against a group of children with insulin induced hypoglycaemia (as part of insulin tolerance test, ITT), it was noted that GH response was significantly lower in children with spontaneous hypoglycaemia." (PMID 24228030, 2013). "Insulin may augment thyroid hormone transcriptional action, and reduce TSH level probably through the effect of hypoglycemia on pituitary-thyroid secretory activity." (PMID 23300866, 2012). "It is particularly interesting that in normal rats the antagonist did not improve or even decrease the response of glucagon to insulin-induced hypoglycemia." (PMID 22969729, 2012). "Hypoglycaemia was not unexpected in this insulin-treated population, particularly considering that 70% were also receiving sulfonylureas." (PMID 22564709, 2012). "Postprandial rebound hypoglycaemia is independent of insulin sensitivity and exercise intensity and does not occur in all individuals, i.e. some individuals are more sensitive than others." (PMID 22780564, 2012).
Hypoglycemia (continued). "On the other hand, serum Zn did not correlate significantly with peak stimulated GH after insulin induced hypoglycemia (r = 0.17, p = 0.31) and clonidine stimulation (r = 0.13, p = 0.23), BA (r = 0.15, p = 0.13) and BA SDS (r = 0.11, p = 0.22)." (PMID 22625223, 2012). "α-cell sensitivity during hypoglycemia improves when normoglycemia is achieved by chronic phloridzin treatment, but not by insulin treatment in diabetic rats." (PMID 22969729, 2012). "Additional objectives include the evaluation of factors associated with optimal glycemic control, hypoglycemia, and treatment adherence among patients with T2DM who do and do not progress beyond their initial insulin therapy." (PMID 22999494, 2012). "Patients with cirrhosis are more prone to hypoglycemia and are not suitable candidates for intensive insulin therapy, either." (PMID 22753144, 2012). "Following discontinuation of cardiopulmonary bypass, when these factors are no longer present, insulin requirements decrease rapidly and if unrecognized, severe hypoglycemia can result." (PMID 23209941, 2012). "She reported no further episodes of hypoglycemia, which was confirmed on 72-hour continuous glucose monitoring with and without prandial insulin." (PMID 22937294, 2012). "Most physicians report that many insulin-treated patients do not have adequate glucose control (87.6%) and that they would treat more aggressively if not for concern about hypoglycaemia (75.5%)." (PMID 22313123, 2012). "S-21663 is an imidazoline compound that is a non glucose-dependent insulin secretagogue, which does not readily induce hypoglycemia." (PMID 27429837, 2012). "In each case of hypoglycemia, this appears to be related to a recent dose of supplemental insulin the patient received (in both treatment groups) and not directly related to sitagliptin therapy." (PMID 23056044, 2012). "In T1D, there is a lack of decrement changes in intraislet insulin occurring which has been postulated to account for the defective glucagon counter-regulation to hypoglycemia." (PMID 22969729, 2012). "Among those participants who were prescribed TZD but not sulfonylurea or insulin, the incidence rate of severe hypoglycemia was similar to that reported in a prescription monitoring program." (PMID 22646230, 2012). "No major hypoglycaemia occurred and minor hypoglycaemia rates were 0.286 and 0.029 events per participant year with and without insulin detemir (9.2% vs. 1.3%)." (PMID 23061886, 2012). "Mortality was non-significantly higher with intensive insulin in studies where the proportion of patients developing hypoglycemia was large (> 33%) (RR 1.17; 95% CI 0.79-1.75; p = 0.44)." (PMID 23082798, 2012). "This triggers insulin release despite the absence of elevated blood glucose levels, resulting in hypoglycaemia." (PMID 23032149, 2012). "If the injection of pre-meal insulin is not timed correctly, then either hyperglycaemia or hypoglycaemia can result, which is a common problem for inpatients with diabetes." (PMID 22613296, 2012). "Use of analog insulin’s such as Lispro (Humalog) in MDI further improved glucose control without increasing the rate of severe hypoglycemia." (PMID 22716962, 2012). "No severe hypoglycemia was reported in the liraglutide-added group, while two patients in the insulin-increasing group reported severe hypoglycemia." (PMID 23153177, 2012). "Although there was an apparent trend toward moderate blunting of insulin-induced hypoglycemia in the knockin animals, the difference was not statistically significant compared to the wild-type mice." (PMID 21195350, 2011). "The in vivo glucose uptake induced by Ad36 is not uncontrolled, as evident from a reduction in circulating glucose and insulin levels observed in Ad36 infected mice, without inducing hypoglycemia." (PMID 21886789, 2011). "Consistent with the glucose-dependent nature of enhanced insulin secretion with exenatide, there were no episodes of major hypoglycaemia throughout the study." (PMID 21434995, 2011).
Hypoglycemia (continued). "Prolonged signaling by insulin bound to the plasma membrane receptor due to the lack of CDE, and consequent insulin-sensitivity has been shown to play a key role in the baseline hypoglycemia, but the most relevant kinase pathways involved were not elucidated." (PMID 21931813, 2011). "Of particular interest, fed ERRα-null mice exhibit time-dependent hypoglycemia and hypoinsulinemia with no apparent impairment in insulin secretion as determined by glucose tolerance tests." (PMID 21731503, 2011). "While we stated in our charter that we did not want to increase our rate of hypoglycemia, our baseline rate was extremely low since so few patients were on an insulin infusion prior to the implementation of this process improvement initiative." (PMID 22091218, 2011). "The fact that there are direct pathways between the nasal cavity and the central nervous system has guaranteed an easy access for insulin through the BBB, without the risk of systemic hypoglycemia that results from the peripheral administration of insulin." (PMID 22654727, 2011). "In HI patients, plasma insulin levels are not frequently high during hypoglycemia, and they remain within the normal range of the laboratory." (PMID 21967988, 2011). "Fasting proinsulin to insulin ratio were significantly improved with sitagliptin treatment while the incidence of hypoglycaemia and gastrointestinal symptoms was not significantly different between sitagliptin and placebo groups." (PMID 22615610, 2010). "If so, it is possible that upregulated pancreatic ghrelin compensates lack of stomach-derived ghrelin and attenuate insulin release, thereby counteracting the hypoglycemia in the late dumping syndrome." (PMID 20721337, 2010). "These are not the most indicated drugs for diabetic patients using insulin as they favor hypoglycemia, unless under specific indications." (PMID 20718958, 2010). "Studies of NPY KO mice showed that feeding in response to insulin-hypoglycemia was absent however hormonal counterregulation was unaltered." (PMID 22022208, 2010). "The long-acting insulin analogs do not have as pronounced a peak effect as NPH insulin and therefore cause less nocturnal hypoglycemia." (PMID 20416099, 2010). "In our experience, in a series of 545 patients with Type 1 DM having difficulty achieving appropriate metabolic control with multiple doses of insulin, we used CGMS with the GlucoDay® system to evaluate the fluctuations of glycemia and the frequency of hypoglycemia." (PMID 22163609, 2010). "In conclusion, COUP-TFII expression is regulated in the VMH by insulin levels aside of circulating glucose and this suggests a possible role as a modulator of the counter regulation engaged by the VMH in response to neuroglucopenia or hypoglycemia." (PMID 20976162, 2010). "The effect of insulin treatment, severe hypoglycemia, at least one psychiatrist visit and no alcohol consumption can be considered as small." (PMID 21044345, 2010). "A study of 100 ICU patients has shown that the incidence of severe hypoglycemia was significantly reduced when insulin was administered by a specific rather than non specific infusion route (4% vs 22%)." (PMID 20840773, 2010). "Higher insulin doses were observed with PP with no between-treatment differences in overall hypoglycaemia or weight gain." (PMID 20880343, 2010). "The insulin dose must be increased by 2-4 units every 3 days until reaching near-normal glycemic levels, with no unexplainable hypoglycemia." (PMID 20718958, 2010). "With respect to the negative challenge, we observed that, the higher the insulin sensitivity, the deepest the glycemia undershoot was, being compensated by a shorter hypoglycemia, and shorter settling times." (PMID 20642855, 2010). "Being an insulin secretagogue, it is as effective as an SU but without significant hypoglycemia and no weight gain." (PMID 21159194, 2010).
Hypoglycemia (continued). "Investigators showed that in a number of situations such as fasting and hypoglycaemia (without exogenous insulin-administration), the adrenal medulla is exclusively stimulated while the SNS is suppressed." (PMID 19442093, 2009). "When the daily insulin dose in a OD regimen nears 40–50 U, intensifying the regimen to BID is a safer way to proceed than simply increasing the dose further, as the dose can be split into two equal doses, which reduces the chance of hypoglycaemia." (PMID 19780866, 2009). "The most probable explanation for the absence of hypoglycemia in our study is the relatively small sample of patients and the short period of intensive insulin treatment in comparison to other studies." (PMID 20003200, 2009). "Their insulin intake did not change during this period and nursing staff had to give them orange juice on several occasions to prevent hypoglycemia." (PMID 18568931, 2008). "Insulin treatment for glycaemic control was safe with respect to blood glucose, because no hypoglycaemia (<80 mg/dl) occurred." (PMID 18218076, 2008). "The patient's last dose of sulphonylurea was prior to admission, 27 days before the onset of hypoglycaemia in hospital and no insulin was administered in the 5 days before hypoglycaemia." (PMID 18644072, 2008). "NICE states that, if target HbA1C with the initial regimen is not reached without problematic hypoglycaemia, patients using a basal regimen should consider additional meal-time doses or switching to a premixed insulin." (PMID 19143853, 2008). "The variations in insulin levels were acute; and did not solely account for the persistent hypoglycemia." (PMID 18793439, 2008). "No consensus was seen regarding insulin's metabolic effects, need for insulin, adequacy of self-monitoring blood glucose, time needed for training and potential for hypoglycaemia in elderly patients." (PMID 18393965, 2008). "In particular, the patient was not receiving exogenous insulin when hypoglycaemia occurred, dextrose was provided in either TPN or intravenous fluids during the episodes and hydrocortisone at stress doses was prescribed for adrenal insufficiency." (PMID 18644072, 2008). "Severe hypoglycaemia did not occur in that study and was also absent from a later study of bedtime insulin and metformin using either NPH or a peakless insulin analogue." (PMID 18215172, 2008). "Post-hoc review of the algorithm performance suggested that cases identified by 962.3 demonstrated low PPV (54%), primarily representing patients with excessive insulin or oral hypoglycemic use without development of clinical or laboratory hypoglycemia." (PMID 18380903, 2008). "Insulinoma is diagnosed with he elevated (or non-suppressed) insulin levels when hypoglycemia occurred." (PMID 19040758, 2008). "The reason CEDAC recommended against reimbursement was that the relatively small improvement in hypoglycemia was not felt to justify the drug's more than 3-fold price relative to NPH (neutral protamine Hagedorn) insulin." (PMID 22058619, 2007). "It should give fast and reliable results that can be used in a nurse-driven insulin infusion algorithm that reduces hyperglycaemia without inducing hypoglycaemia." (PMID 16981981, 2006). "GRIP, a computer decision support system for glucose control by intensive insulin therapy, exhibited efficient glucose control without inducing severe hypoglycemia during a 4 month period." (PMID 16359559, 2005). "It is characterized by spontaneous hypoglycemia, extremely high insulin levels, and the presence of circulating insulin antibodies in patients who have never been exposed to exogenous insulin." (PMID 15543375, 2004). "He said he had not been using exogenous insulin and was unaware of cases of hypoglycemia in his family." (PMID 15543375, 2004). "Fifth, hypothalamic function could not be directly assessed using insulin-induced hypoglycemia or other definitive tests because of safety concerns in patients with long COVID." (PMID 41596479, 2026).